KCNMB4 (potassium calcium-activated channel subfamily M regulatory beta subunit 4)
Description:
Regulatory subunit of the calcium activated potassium KCNMA1 (maxiK) channel. Modulates the calcium sensitivity and gating kinetics of KCNMA1, thereby contributing to KCNMA1 channel diversity. Decreases the gating kinetics and calcium sensitivity of the KCNMA1 channel, but with fast deactivation kinetics. May decrease KCNMA1 channel openings at low calcium concentrations but increases channel openings at high calcium concentrations. Makes KCNMA1 channel resistant to 100 nM charybdotoxin (CTX) toxin concentrations.
Tractability: Small molecule: a structure with a bound ligand is known. Antibody: its Gene Ontology location is reachable by antibodies, with high confidence; UniProt predicts a signal peptide or a membrane-spanning region.
Gene: Protein-coding gene on chromosome 12 (70,366,290 to 70,434,292, forward strand). Ensembl gene ENSG00000135643.
Subcellular location: Membrane
Subcellular location (Human Protein Atlas): Cytosol
Pathways (Reactome):
Hemostasis: cGMP effects
Neuronal System: Ca2+ activated K+ channels
Gene Ontology:
Molecular function: calcium-activated potassium channel activity; protein binding; potassium channel regulator activity; voltage-gated monoatomic ion channel activity involved in regulation of presynaptic membrane potential
Biological process: action potential; detection of calcium ion; neuronal action potential; potassium ion transport; chemical synaptic transmission; regulation of neurotransmitter secretion; regulation of vasoconstriction; potassium ion transmembrane transport; regulation of presynaptic membrane potential
Cellular component: plasma membrane; voltage-gated potassium channel complex; membrane; synapse
Genetic constraint (gnomAD): Loss-of-function variants: 2 observed, 15.78 expected, observed/expected ratio (o/e) 0.13, 90% interval 0.051 to 0.4. The upper end of that interval is the gene's LOEUF score, 0.4, which puts it in group 1 of 6, group 1 being the genes least tolerant of losing a copy. Missense variants: 154 observed, 247.92 expected, observed/expected ratio (o/e) 0.62, 90% interval 0.54 to 0.71. Synonymous variants: 106 observed, 109.47 expected, observed/expected ratio (o/e) 0.97, 90% interval 0.83 to 1.14.
Homologues: Orthologues: chimpanzee KCNMB4 (100% identical), macaque KCNMB4 (100% identical), pig KCNMB4 (99% identical), rabbit KCNMB4 (99% identical), dog KCNMB4 (95% identical), rat Kcnmb4 (94% identical), mouse Kcnmb4 (94% identical), tropical clawed frog kcnmb4 (72% identical). Paralogues in human: KCNMB2 (30% identical), KCNMB3 (30% identical), KCNMB1 (21% identical).
Diseases named in the same sentence as KCNMB4 in open-access papers:
KCNMB4 is named in the same sentence as 12 diseases in open-access papers, as found by Europe PMC text mining. Sharing a sentence is not in itself a finding about the gene and the disease. The quoted sentences say what the papers report.
osteosarcoma (2 papers, 2014 to 2023). A usually aggressive malignant bone-forming mesenchymal neoplasm, predominantly affecting adolescents and young adults. "We sought to detect chimeric KCNMB4-CCND3 and LRP1-SNRNP25 protein products in 31 human osteosarcoma tissues by western blotting with antibodies against CCND3, KCNMB4, SNRNP25 and LRP1." (PMID 25300797, 2014). "A recurrent fusion gene between KCNMB4 and CCND3 has also been identified in a cohort of osteosarcoma, but not in a cohort of 240 other sarcomas, further suggesting a specific role of CCND3 in osteosarcoma." (PMID 37510349, 2023).
Alzheimer disease (1 paper, 2024). A progressive, neurodegenerative disease characterized by loss of function and death of nerve cells in several areas of the brain leading to loss of cognitive function such as memory and language. "Microglia express GPNMB in the brains of Alzheimer's disease and Nasu-Hakola disease, PRKCA is associated with neural basis of episodic remembering in healthy individuals and KCNMB4 is downregulated in hippocampal granule neurons following seizure activity." (PMID 38632500, 2024).
nasopharyngeal carcinoma (1 paper, 2026). A carcinoma arising from the nasopharyngeal epithelium. "We demonstrate that PRMT5 facilitated paclitaxel resistance by inducing KCNMB4 expression in nasopharyngeal carcinoma cells." (PMID 41513606, 2026).
temporal lobe epilepsy (1 paper, 2025). A localization-related (focal) form of epilepsy characterized by recurrent seizures that arise from foci within the temporal lobe, most commonly from its mesial aspect. "Deletion of the KCNMB4 gene coding the β4 subunit increases firing in hippocampal dentate granule cells, leading to temporal lobe epilepsy." (PMID 41465576, 2025).
cancer (2 papers, 2021 to 2026). A tumor composed of atypical neoplastic, often pleomorphic cells that invade other tissues. "Stable knockdown of KCNMB4 also reduced the tumorsphere formation ability of 5-8 F R cells under paclitaxel treatment, suggesting a loss of cancer stemness." (PMID 41513606, 2026). "In particular, the GSE34053 dataset analyzed cancer-associated fibroblasts (CAF, tumor stromal cells) and CD133+ cells (tumor epithelial cells); while CD133+ cells expressed higher levels of KCNAB2 and KCNMB4, CAF cells (stroma) overexpressed SCN9A and KCNJ8 subunit channels." (PMID 33802791, 2021).
infection (1 paper, 2022). The state of being infected such as from the introduction of a foreign agent such as serum, vaccine, antigenic substance or organism. "We propose that our results convincingly suggest that circ_3205 is a circRNA synthesized by SARS-CoV-2 upon host cell infection and that it may behave as a competitive endogenous RNA (ceRNA), sponging hsa-miR-298 and contributing to the upregulation of KCNMB4 and PRKCE mRNAs." (PMID 35039944, 2022).
KCNMB4 also shares sentences with these, for which no sentence is quoted: autism (1 paper); glioma (1); Nasu-Hakola disease (1); Polyuria (1); tumor (1); type 2 diabetes mellitus (1).